TCF7L2 (transcription factor 7 like 2)
Diseases named in the same sentence as TCF7L2 in open-access papers (continued):
Sharing a sentence is not in itself a finding about the gene and the disease.
demyelinating disease (1 paper, 2013). A broad group of disorders that affect the myelin sheaths that cover the neurons. "To determine whether the reexpression of TCF7L2 is restricted to demyelinating diseases such as MS, we stained ten tissue samples from eight patients with inflammatory but non demyelinating diseases (e.g. encephalitis, vasculitis)." (PMID 23977356, 2013). "However, reexpression of TCF7L2 is neither limited to the oligodendroglial lineage nor to demyelinating lesions since we found a marked expression of this transcription factor in oligodendrocytes and astrocytes in inflammatory, non demyelinating diseases." (PMID 23977356, 2013).
dilated cardiomyopathy (1 paper, 2012). Cardiomyopathy which is characterized by dilation and contractile dysfunction of the left and right ventricles. "Among these reported genes, two genes (ADCY5 and TCF7L2) were also found annotated to ARVC and dilated cardiomyopathy pathways." (PMID 22973544, 2012).
endometrial cancer (1 paper, 2023). Primary or metastatic malignant neoplasm involving the endometrium (mucous membrane that lines the endometrial cavity). "By transcriptomic analysis, we identify LEF1 signalling as upregulated in Fbxw7/FBXW7‐mutant mouse and human endometrial cancers, and in human isogenic cell lines carrying FBXW7 mutation, and validate LEF1 and the additional Wnt pathway effector TCF7L2 as novel FBXW7 substrates." (PMID 37589076, 2023). "Whether TCF7L2 dysregulation contributes to FBXW7‐mutant endometrial cancer is less clear." (PMID 37589076, 2023).
endothelial dysfunction (1 paper, 2023). In vascular diseases, endothelial dysfunction is a systemic pathological state of the endothelium (the inner lining of blood vessels) and can be broadly defined as an imbalance between vasodilating and vasoconstricting substances produced by (or acting on) the endothelium. "In subarachnoid hemorrhage rats, bone marrow mesenchymal stem cell-derived extracellular vesicles could alleviate endothelial dysfunction by regulating the KLF3-AS1/miR-183-5p/TCF7L2 signaling axis." (PMID 37396583, 2023).
gallbladder cancer (1 paper, 2024). "This study explores epigenetic mechanisms underlying oncogenesis of gallbladder cancer (GBC), revealing SOX9 and TCF7L2 can form a core regulatory circuitry (CRC) to drive oncogenic SE reprogramming and subsequent transcriptional activation of critical malignant genes." (PMID 39492805, 2024).
ganglioglioma (1 paper, 2023). A well differentiated, slow growing neuroepithelial neoplasm composed of neoplastic, mature ganglion cells and neoplastic glial cells. "PAX6, MEIS1, and TCF7L2 concentrations as well as SCENIC-calculated regulon scores correlated strongly with ganglioglioma neoplastic cell stemness by CellRank/CytoTRACE pseudotime or SCENT signaling entropy rate." (PMID 36966348, 2023).
hemochromatosis (1 paper, 2024). A disorder of iron metabolism characterized by a triad of HEMOSIDEROSIS; LIVER CIRRHOSIS; and DIABETES MELLITUS. "Seven GMs, including ABCC1, ADRB2, EDNRA, hemochromatosis (HFE), HLA, interleukin 8 (IL-8), TCF7L2, and SLC11A1, had two studies conducted." (PMID 40225935, 2024).
hypertrophic cardiomyopathy (1 paper, 2016). A condition in which the myocardium is hypertrophied without an obvious cause. "Several additional pathways identified, including calcium signaling, hypertrophic cardiomyopathy, and ARVC, are also enriched among TCF7L2 target genes in colorectal cancer." (PMID 27333864, 2016).
intervertebral disc degeneration (1 paper, 2024). "Using real-time quantitative polymerase chain reaction (qRT-PCR) analysis, we validated the expression levels of two core genes, IL1R1 and TCF7L2, in the Intervertebral Disc Degeneration (IDD) group compared to the normal intervertebral disc group." (PMID 39050860, 2024). "Inhibiting TCF7L2 may hold therapeutic potential for intervertebral disc degeneration (IDD), as related research has shown a close association between TCF7L2 and the development of IDD." (PMID 39050860, 2024). "This study comprehensively analyzed the pathogenesis of Intervertebral Disc Degeneration (IDD) and identified potential target genes, IL1R1 and TCF7L2, closely related to the progression of IDD." (PMID 39050860, 2024).
intestinal polyposis (1 paper, 2021). "fl-Tcf4 and dnTcf7 transcripts are the predominant Tcf/Lef1 family isoforms expressed in the intestine, which explains the opposite intestinal phenotypes in mice deleted of Tcf7l2 (lack of cycling stem cells) versus Tcf7 (intestinal polyposis)." (PMID 34788095, 2021).
lung diseases (1 paper, 2015). "TCF7 interacts with multiple proteins and target genes (e.g. CD3E, β-catenin, TCF7L2, LEF-1, IL-17, IL-4, or Eomes) and is involved in several signal pathways (e.g. Wnt, FoxO1, Notch, or P21pathways) which are critical for lung diseases, especially the canonical Wnt/β-catenin pathway." (PMID 26289446, 2015).
malaria (1 paper, 2023). Malaria is a serious and sometimes fatal disease caused by a parasite that commonly infects a certain type of mosquito which feeds on humans. "We also found the TCF7L2 variant, rs7903146 to be associated with susceptibility to developing severe malaria in children from Ibadan southwest Nigeria." (PMID 37215099, 2023). "In order to test this hypothesis, we genotyped a TCF7L2 gene variant (rs7903146) in Nigerian children with malaria in a pilot study and found the gene to be present in the population." (PMID 37215099, 2023).
meningioma (1 paper, 2012). A generally slow growing tumor attached to the dura mater. "With respect to downstream gene sets of PI3K/Akt pathway, proliferation-promoted genes such as CTNNB1, CREB1, CREB5, and TCF7L2 were up-regulated in fibroblastic meningioma." (PMID 23285163, 2012).
metastatic cancers (1 paper, 2024). A carcinoma which has spread from the original site of growth to another anatomic site. "In particular, co-mutations of APC with TCF7L2 or SOX9 may identify a subgroup of metastatic cancers with favorable prognosis." (PMID 39587554, 2024).
non-small cell lung carcinoma (1 paper, 2024). A group of at least three distinct histological types of lung cancer, including non-small cell squamous cell carcinoma, adenocarcinoma, and large cell carcinoma. "During non-small cell lung cancer (NSCLC), miR-495 targets Tcf7l2, and inactivates the Wnt/β-catenin pathway to inhibit progression." (PMID 39664574, 2024).
Pitt-Hopkins syndrome (1 paper, 2023). Pitt-Hopkins syndrome (PHS) is characterized by the association of intellectual deficit, characteristic facial dysmorphism and problems of abnormal and irregular breathing. "Pitt Hopkins Syndrome (PTHS) is a rare neurodevelopmental disorder resulting from autosomal dominant mutations on chromosome 18 at the TCF4 (also known as ITF2, SEF2, E2-2, not T-cell factor 4 which is encoded by TCF7L2 gene) locus." (PMID 36224259, 2023).
pituitary tumours (1 paper, 2024). "To elucidate these aspects, we examined the structural alternation and expression levels of TCF7L2 in pituitary tumours, aiming to understand its potential role and regulatory mechanisms in tumourigenesis." (PMID 38769659, 2024). "Given the critical role of TCF7L2 in the Wnt signalling pathway, its structural and expressional dynamics in pituitary tumours are not well characterised." (PMID 38769659, 2024).
Sciatica (1 paper, 2021). Pain in the lower back and hip radiating in the distribution of the sciatic nerve. "AZU1, BPI, TCF7L2, and WFIKKN1 were upregulated in sciatica patients, while ANGPTL4, CRP, EREG, FAM19A4, FGF1, LOC100129216, PLXNB1, RLN1, and RXFP2 were downregulated." (PMID 34925462, 2021).
stable angina (1 paper, 2025). "Longitudinal studies are warranted to confirm the role of TCF7L2 gene polymorphisms in relation to the risk of stable angina and ACS." (PMID 40303486, 2025). "This study examined the relationship between the TCF7L2 gene variant rs77961654 A/C and the risk of stable angina and ACS." (PMID 40303486, 2025). "The first key finding of this study is that the TCF7L2 CC genotype was more prevalent in the patients with stable angina and ACS than in the controls." (PMID 40303486, 2025). "There was a significant difference in TCF7L2 genotype distribution between the stable angina/ACS groups and control group (p < 0.0001)." (PMID 40303486, 2025). "A higher prevalence of the CC genotype was observed in both the stable angina and ACS groups, suggesting an association between TCF7L2 gene polymorphisms and the presence of stable angina and ACS." (PMID 40303486, 2025). "Moreover, Pearson's correlation analysis revealed that the TCF7L2 CC genotype was positively correlated with both stable angina (r = 0.144, p < 0.0001) and ACS (r = 0.193, p < 0.0001)." (PMID 40303486, 2025). "Conversely, the TCF7L2 AA genotype was negatively correlated with ACS (r = -0.084, p = 0.022), and the TCF7L2 AC genotype was negatively correlated with both stable angina (r = -0.114, p = 0.001) and ACS (r = -0.131, p = 0.0003)." (PMID 40303486, 2025). "In addition, we could not infer causality between TCF7L2 rs77961654 A/C variants with the risk of stable angina and ACS due to the cross-sectional design of the study." (PMID 40303486, 2025). "We also analyzed the frequency of T2DM status (absence or presence of T2DM) in the patients with stable angina and ACS, stratified by TCF7L2 genotypes." (PMID 40303486, 2025).
T-cell leukemia (1 paper, 2021). A malignant disease of the T-lymphocytes in the bone marrow, thymus, and/or blood. "Transcription Factor 7-Like 2 (TCF7L2), also known as TCF4 transcription factor, is a key effector for the activation of Wnt signaling pathway in adult T cell leukemia cells." (PMID 34926267, 2021).
cancer (118 papers, 2006 to 2026). A tumor composed of atypical neoplastic, often pleomorphic cells that invade other tissues. "Mutations in CDKN1B and TCF7L2 have been implicated in the initiation and progression of various cancers." (PMID 40658092, 2025). "TCF7L2 has been associated with type 2 diabetes (T2D), chronic renal disease, and cancer, including BC and hepatocarcinoma." (PMID 40149317, 2025). "Several genes have been identified that increase the susceptibility both to T2DM and cancer development (e.g., TCF7L2, CDKN2A/B, AKT2, PPARG, PTEN and HNF1B) but the evidence for a common etiology of both conditions is scarce." (PMID 38835644, 2024). "Among genes participating in this signaling pathway, AXIN2 and TCF7L2 have shown an association with different cancers." (PMID 35996498, 2022). "Several studies have investigated the association of the AXIN2 and TCF7L2 polymorphisms with cancer." (PMID 35996498, 2022). "Transcription factor 7-like 2 (TCF7L2), an established inducer of epithelial-to-mesenchymal transition and associated cancer invasion, was significantly upregulated in widely invasive tumors specifically (p<0.05)." (PMID 33063251, 2020). "A previous study evaluated the potential association between TCF7L2 rs290481 variants and cancer risk in Chinese patients with T2D." (PMID 31211453, 2019). "Nevertheless, TCF7L2: rs4506565 should be further investigated in future research for potential associations with cancer metastasis." (PMID 28732081, 2017). "TCF7L2 single-nucleotide polymorphisms (SNPs) are proposed susceptibility factors for the development of cancer." (PMID 29312594, 2017). "Pooled ORs and 95%CIs of the association between TCF7L2 rs7903146 (or its proxy rs12255372) polymorphism and cancer risk." (PMID 23951231, 2013). "Characteristics of included studied of association between TCF7L2 rs7903146 (or its proxy rs12255372) polymorphism and cancer risk." (PMID 23951231, 2013). "A total of 14814 cases and 33856 controls were identified for the analysis of the association between TCF7L2 polymorphism with cancer risk." (PMID 23951231, 2013). "At last, 19 studies for the association between TCF7L2 polymorphism and cancer risk were included in the final meta-analysis." (PMID 23951231, 2013). "A total of 19 studies (14,814 cases and 33,856 controls) were identified for the analysis of the association between TCF7L2 polymorphism and cancer risk." (PMID 23951231, 2013). "We found significant between-study heterogeneity in the association of TCF7L2 rs7903146 polymorphism with cancer risk." (PMID 23951231, 2013). "Further studies are necessary to examine the potential different mechanisms of TCF7L2 polymorphism in various cancers." (PMID 23951231, 2013). "In this study, we performed a meta-analysis to clarify the associations between TCF7L2 polymorphism and cancer risk." (PMID 23951231, 2013). "We chose these particular cell lines because TCF7L2 has been associated with these types of cancers and because all of these cells have various data sets associated with them as part of the ENCODE project." (PMID 22951069, 2012). "Silencing of TCF7L2 causes sensitivity of cancer cells to X-ray." (PMID 38585634, 2024). "Several meta-analyses have evaluated cancer risk induced by TCF7L2 gene variants." (PMID 34305772, 2021). "Genetic variations in transcription factor 7-like 2 (TCF7L2) are associated with cancer risk." (PMID 27738320, 2016). "Prior to its association with T2D, TCF7L2 was identified as a cancer gene." (PMID 24719615, 2014). "TCF7L2 is an integral member of Wnt signaling, and a number of the pathways regulated by Tcf7l2 silencing in our study have been linked to Wnt activity in numerous tissues and cells, including those related to cell growth, differentiation and cancer." (PMID 25414334, 2014). "Therefore, we performed a meta-analysis to clarify the association between TCF7L2 rs7903146 variant and cancer risk." (PMID 23951231, 2013).
cancer (continued). "Aberrant TCF7L2 expression modifies Wnt signaling and mediates oncogenic effects through the upregulation of c-MYC and cyclin D. Genetic alterations in TCF7L2 may therefore affect cancer risk." (PMID 17109766, 2006). "As TCF7L2 gene variation may be involved in T2D development and in different mechanisms of other pathologies, such as those related to hyperglycemia, the pathophysiological mechanisms‐related pathways are in turn strongly linked to cancer etiology." (PMID 34612510, 2022). "The molecular mechanism of TCF7L2 gene polymorphisms and altered cancer risk remains unclear." (PMID 27738320, 2016). "An exception is the positive association between TCF7L2 alleles and higher risk of both T2DM and breast and colorectal cancer; and, also the association between type 2 diabetes predisposing alleles, and lower risk of prostate cancer." (PMID 38835644, 2024). "In this study, we identify TCF7L2 as a major driver of lipid-based metabolic reprogramming in ccRCC, supporting cancer cell invasion potential through the activation of EMT." (PMID 38390305, 2024). "In contrast to FOXP2, genetic alternations in Transcription Factor 7 Like 2 (TCF7L2), the focus on the current study, is reportedly associated with human diseases, including metabolic disorders and cancers." (PMID 36782064, 2023). "Kyoto encyclopedia of genes and genomes (KEGG) analysis showed that hsa_circ_0004099 was enriched in several cancer pathways, which were collectively enriched in four genes namely TCF7L2, NRAS, CTNNB1, and KRAS." (PMID 36399471, 2022). "A clear example is within cancer, where, if oversimplified, the Wnt/β‐catenin signaling and TCF7L2 pathways can be considered oncogenic or tumor‐suppressive." (PMID 34612510, 2022). "Zinc finger protein ZIC2 (ZIC2) has been found to interact with TCF7L2, enabling it to act as a Wnt/β-catenin signaling inhibitor, thus regulating Wnt signaling which has been found to be upregulated in several cancers." (PMID 33114107, 2020). "Immunostaining of candidate proteins MAX, TCF7L2, YY1, IRF1, STAT6, SP1, and E2F1 (selected based on qPCR results and/or associations to cancer in general) was performed in additional FTC specimens as outlined in the “Materials and Methods” section." (PMID 33063251, 2020). "We identified that TCF7L2 rs290481, INS rs689, and INSR rs1799817 SNPs increased the susceptibility of AEG in different cancer stage subgroups." (PMID 31211453, 2019). "The results from the five-gene signature (adding two genes: TCF7L2 and HLA-C) showed 13 different cancer studies." (PMID 30287838, 2018). "As shown, knockdown of TCF7L2 significantly reduced cancer cell viability of PANC-1 and MIA PaCa-2 cells." (PMID 29476053, 2018). "Previous studies have demonstrated that ITF-2 is a downstream target of the Wnt/β-catenin/ TCF7L2 pathway, which is frequently disrupted in human cancers." (PMID 28574827, 2017). "In this paper, we first describe the workflow of T-cep, then present training results on TCF7L2-omics data in five cancer cell types, and compare it with ChromHMM." (PMID 28499350, 2017). "These included several candidate tumor suppressor genes, such as ABLIM1, CYFIP2, VPS13A, SERPINI1, TET2, HTRA4, UBE2L6, as well as oncogenes/genes implicated as biomarkers in other cancers, such as FAM65B and TCF7L2." (PMID 27385100, 2016).